SLC12A5 (solute carrier family 12 member 5)
Diseases named in the same sentence as SLC12A5 in open-access papers (continued):
Sharing a sentence is not in itself a finding about the gene and the disease.
cancer (20 papers, 2014 to 2025). A tumor composed of atypical neoplastic, often pleomorphic cells that invade other tissues. "Since the NKCC1 mutation has a prominently prognostic value on pan-cancer patients, we further analyzed the KCC2 (SLC12A5) and NKCC1 (SLC12A2) mutation, and we then queried 48,834 samples in 188 studies for a comprehensive analysis." (PMID 35372048, 2022). "Collectively, we uncover that SLC12A5 is remarkably associated with prognosis and progression of human cancers." (PMID 34630736, 2021). "SLC12A5 is implicated in an oncogenic capacity and facilitates the progression of cancer." (PMID 38780503, 2024). "We further integrated our methylation results with RNA-seq data, and we identified 11 genes, including six related to immune functions (AHR, LRFN5, NTRK2, RSPO2, SAMSN1, and TFEC), and three related to cancer (SLC12A5, SORCS1, and TP63)." (PMID 39795948, 2024). "After discovering that DNA variation of KCC2 (SLC12A5) and NKCC1 (SLC12A2) affect the prognosis of cancer patients, we conducted a specific analysis of CCC mutation in cancer samples from TCGA database." (PMID 35372048, 2022). "We further explored the prognostic values of SLC12A5 in human cancers using the Cox analysis and Kaplan-Meier survival method." (PMID 34630736, 2021). "In this research, we comprehensively analyzed the expressing patterns, prognostic values, and clinical significances of SLC12A5 in pan-cancers." (PMID 34630736, 2021). "The results reflected the different regulatory relationships between SLC12A5 and immunosuppressive molecules in different cancers." (PMID 34630736, 2021). "Despite this, there has been limited reporting on the effects of SLC12A5 in human cancers." (PMID 38780503, 2024). "Likewise, cell cycle progression was inhibited by PNCK knockdown in SLC12A5 overexpressing‐cancer cells." (PMID 36645171, 2023). "We found 390 cases of mutations of KCC2 (SLC12A5) and NKCC1 (SLC12A2) in cancers." (PMID 35372048, 2022). "For human cancers, the expression and function of SLC12A5 were rarely reported." (PMID 34630736, 2021). "Herein, we comprehensively and systematically explored the roles of SLC12A5 in 33 human cancers." (PMID 34630736, 2021). "Furthermore, we noticed that SLC12A5 was distinctly associated with methyltransferases, mismatch repair proteins, TMB, and MSI in human cancers." (PMID 34630736, 2021). "SLC12A5 may act as a potential prognostic and immunological biomarker and therapeutic target for human cancers." (PMID 34630736, 2021). "However, similar studies of SLC12A5 in other cancer types remained in infancy." (PMID 34630736, 2021). "Additionally, the compelling evidences of SLC12A5 protein levels in human cancers are insufficient." (PMID 34630736, 2021). "Among of them, SLC12A5, MYO1B, FBN1, ITGAV, KLF4 and USP28 were more reported to effect cell proliferation and migration in human cancers." (PMID 39951205, 2025). "To investigate differential cation-chloride transportation patterns in tumors, we analyzed the differential expression of KCC2 (SLC12A5) and NKCC1 (SLC12A2) in pan-cancer tissues from TCGA database and normal samples from TCGA and GTEx Portal databases." (PMID 35372048, 2022). "Next, we found that KCC2 (SLC12A5) and NKCC1 (SLC12A2) have a high frequency of CNV in pan-cancer, and significantly interfere with prognosis for cancer patients." (PMID 35372048, 2022). "Taken together, cation-chloride cotransporters KCC2 (SLC12A5) and NKCC1 (SLC12A2) have a certain impact on the survival of patients in pan-cancer, especially in KIRC, GBM, PRAD, THCA, BLCA, and CESC." (PMID 35372048, 2022). "SLC12A5 (also known as KCC2), an integral membrane potassium-chloride cotransporter mainly involved in maintaining chloride homeostasis in neurons, has recently been reported as a potential prognostic biomarker for human cancer." (PMID 39507421, 2024).
cancer (continued). "Considering that SLC12A5 is an oncogene, we investigated whether VU0240551, a selective SLC12A5 antagonist, could prevent growth and induce cancer cell death." (PMID 36645171, 2023). "Furthermore, we conducted a detailed Kaplan–Meier survival analysis of the specific effects of KCC2 (SLC12A5) and NKCC1 (SLC12A2) on patient survival in various cancers." (PMID 35372048, 2022). "Next, we analyzed all TIME elements and the enrichment scores of KCC2 (SLC12A5) and NKCC1 (SLC12A2) in pan-cancer, and found that the expression of KCC2 was significantly correlated with the increase in the number of immune cells, including B cells, Th2 cells, and M1 macrophages." (PMID 35372048, 2022). "In addition, we studied the relationship between the expression of KCC2 (SLC12A5) and NKCC1 (SLC12A2) in pan-cancer and immune checkpoint genes, including SIGLEC15, IDO1, CD274, HAVCR2, PDCD1, CTLA4, LAG3, and PDCD1LG2." (PMID 35372048, 2022). "Importantly, we analyzed the survival difference between the altered and unaltered group of KCC2 (SLC12A5) and NKCC1 (SLC12A2) among cancer patients from 66 databases." (PMID 35372048, 2022). "Importantly, we analyzed the survival difference between the altered and unaltered group of KCC2 (SLC12A5) and NKCC1 (SLC12A2) among 10,967 pan-cancer patients, including disease-specific survival (DSS), PFS, and OS." (PMID 35372048, 2022). "We noticed that SLC12A5 expression was distinctly correlated with the level of immune infiltration of B cells in 15 types of cancers, CD8+ T cells in 10 types of cancers, CD4+ T cells in 22 types of cancers, and macrophages in 16 types of cancers." (PMID 34630736, 2021). "Solute carrier family 12 member 5 (SLC12A5), an integral membrane KCl cotransporter, which maintains chloride homeostasis in neurons, is aberrantly expressed and involved in the tumorigenesis of certain cancers." (PMID 28333147, 2017). "In this study, we hypothesized that KCC2 (SLC12A5) and NKCC1 (SLC12A2), the major cation-chloride transporters, could predict the occurrence and development of cancers by regulating ion channels in pan-cancer, which may provide promising potential targets for clinical management strategies." (PMID 35372048, 2022).
peripheral nervous system diseases (1 paper, 2021). "Solute carrier family 12 member 5 (SLC12A5) encodes K+-Cl− cotransporter 2, which is related to various central and peripheral nervous system diseases." (PMID 34630736, 2021).
SLC12A5 also shares sentences with these, for which no sentence is quoted: Rett syndrome (29 papers); Stroke (20); autism spectrum disorder (14); depression (12); ischemia (12); Alzheimer disease (11); Anxiety (11); brain disorder (11); cognitive deficits (11); psychiatric disorder (11); Huntington disease (10); idiopathic generalized epilepsy (10); status epilepticus (10); spinal cord injury (8); Epileptic encephalopathy (6); infection (6); brain injury (5); cervical cancer (5); developmental delays (5); Hyperammonemia (5); neurodegenerative disease (5); peripheral nerve injury (5); respiratory failure (5); cognitive decline (4); Down syndrome (4); epilepsy of infancy with migrating focal seizures (4); injury (4); Parkinson disease (4); bipolar disorder (3); cognitive disorder (3).
A further 97 diseases each share a sentence with SLC12A5 in 3 papers or fewer.